LGR5 (leucine rich repeat containing G protein-coupled receptor 5)
Diseases named in the same sentence as LGR5 in open-access papers (continued):
Sharing a sentence is not in itself a finding about the gene and the disease.
colon carcinoma (continued). "In an organoid model, colon cancer stem cells expressing the Leucine Rich Repeat Containing G Protein-Coupled Receptor 5 (LGR5) and p27 are in dormancy and this state is regulated by cell–matrix interactions." (PMID 39682261, 2024). "Balance of BMP and Wnt signaling is crucial for Lgr5+ ISCs maintenance and colon cancer development." (PMID 39433900, 2024). "The LoVo colon cancer cell line has previously been shown to express sufficient levels of LGR5 for antibody detection." (PMID 39169164, 2024). "It is important to note that LGR5 expression is decreased in advanced stages of colon cancer; hence, when RSPO1/LGR5 stimulates TGFβ signaling, it leads to the inhibition of tumor growth and induction of apoptosis." (PMID 39183418, 2024). "The best-established CSC biomarker for colorectal is probably Lgr5, which is required for the maintenance of spheroid-derived colon cancer stem cells." (PMID 38339195, 2024). "Ablation of Lgr5 positive cells in the primary tumor in mice restricted metastatic progression of colon cancer cells." (PMID 38659853, 2024). "In models of colon cancer, a mutation in PIK3CA activates PI3K/Akt signaling and increases the expression of LGR5 and c-myc, promoting the survival and proliferation of stem cells." (PMID 38892410, 2024). "FXR-KO mice exhibited elevated colon cancer markers (β-catenin, LGR5, CD44, CD34, and cyclin D1) under LPS, underscoring the pivotal role of FXR in inhibiting the development of colon tumorigenesis." (PMID 38069256, 2023). "Next, we investigated the predictive value of combining the mRNA expression levels (low and high) of WNT5A and LGR5 in colon cancer tissues and then correlated them with the overall survival of the patients." (PMID 37998393, 2023). "Next, we investigated how WNT5A and LGR5 protein expression levels in colon cancer tissue were related to the overall survival of patients." (PMID 37998393, 2023). "Our flow cytometry experiments revealed that a high dose of EUG (500 μM) effectively decreases the population of CD44+, CD133+, and LgR5+ cells in a metastatic colon cancer cell line." (PMID 36831488, 2023). "The fact that β-catenin signaling stimulates the colon cancer stem cell niche explains why LGR5 has been recognized and used as a colon cancer stem cell marker." (PMID 37998393, 2023). "Expression of WNT5A (a tumor suppressor) negatively correlated with that of LGR5/RSPO3 (tumor promoters) in colon cancer cohorts." (PMID 37998393, 2023). "To validate our WNT5A and LGR5 survival results, we assessed data for 274 patients from the colon cancer cohort TCGA-COAD who provided colon cancer tissue mRNA samples." (PMID 37998393, 2023). "To investigate such a possible mechanism, we started by assessing the correlation between WNT5A and LGR5 expression levels in one and the same colon cancer patient cohort." (PMID 37998393, 2023). "There are several possible explanations for such discrepancies, including different isoforms of DCLK1, the plasticity of LGR5 expression and the presence of different subpopulations of colon cancer stem cells." (PMID 37998393, 2023). "Like the Apcloxp/loxp: Lgr5-EGFP-IRES-CreERT2 mouse model, refeeding augmented small intestinal and colonic tumour formation, highlighting that post-fast refeeding enhances intestinal tumourigenicity, including those derived from Lgr5+ ISCs." (PMID 36711807, 2023). "Junttila and colleagues report an interesting approach to the use of antibody‐drug conjugates (ADCs) targeting LGR5+ cells to treat colon cancer." (PMID 37578396, 2023). "SW480 colon cancer cells were stimulated with Foxy5 for 24 h followed by double staining with both an anti-LGR5 antibody and an anti-β-catenin antibody." (PMID 37998393, 2023). "The results regarding WNT5A signaling, LGR5 expression and the growth of colon cancer cells are in line with the role of LGR5 in promoting β-catenin-dependent signaling." (PMID 37998393, 2023).
colon carcinoma (continued). "The demonstration that RSPO3 is a driver of intestinal cancer, and the fact that LGR5 is a WNT/β-catenin signaling target urged us to explore a possible relationship between RSPO3 and LGR5 as well as WNT5A signaling in colon cancer tissues." (PMID 37998393, 2023). "Lgr5 is another stem gene for intestine epithelial cells and is often highly expressed in colon cancer patients." (PMID 36386200, 2022). "Lgr5 was proved to be expressed in gastrointestinal crypt stem cells and can also be used to identify tumor stem cells in colon cancer." (PMID 36465343, 2022). "Because selective depletion of colon Lgr5 + CSCs prevented liver metastasis, the experimental evidence has proven that colon cancer-derived liver metastasis depends on a specific subpopulation of Lgr5 + cells." (PMID 36348319, 2022). "A recent publication also showed that the Lgr5-Tnfrsf19 interaction is able to activate NF-κB in colon carcinoma cell lines." (PMID 34751748, 2021). "LGR5 was originally isolated from colon cancer cells, where 56% LGR5(+) cells were observed in colorectal CSCs." (PMID 33713277, 2021). "Another example of ADC targeting the Wnt pathway is the specific LGR5 mAb conjugated to the cytotoxic drug auristatin, which showed efficacy in vivo in a xenograft colon cancer model." (PMID 33668092, 2021). "In the present study, we identified that Zic2 enhances Wnt signaling and initiates the transcription of several novel downstream target genes, including cyclin D1, CD44, and Lgr5, which promote proliferation and stemness in colon cancer cells." (PMID 34099631, 2021). "This was also confirmed in vivo, where HNK treatment significantly reduced the expression of DCLK1 and LGR5 in the colonic tumors." (PMID 34206989, 2021). "Colon cancer CSCs overexpress LGR5, which results in increased numbers of antiapoptotic Bcl-2 and BcL-xL genes." (PMID 34577576, 2021). "Mll1 is highly expressed in Lgr5+ stem cells and human colon carcinomas with increased nuclear β-catenin." (PMID 33349639, 2020). "Genetic ablation of Lgr5+ stem cells by diptheria toxin halts colon cancer growth, revealing the relevance of these stem cells for tumorigenesis." (PMID 33349639, 2020). "Epigenetic methylation of Lgr5 is commonly observed in the colon cancer patients, who have higher tumor grades and poor prognosis." (PMID 31901081, 2020). "It adds to previous reported Wnt/β-catenin independent role of Rspo1 in antagonizing colon cancer metastasis, in which LGR5 directly binds to TGFβ receptors for the activation of TGFβ signaling." (PMID 32749219, 2020). "In support, previous studies indicated that increased LGR5 expression was identified in drug-resistant colon cancer cells and was a key player in generating/maintaining colon cancer stem cells." (PMID 32560222, 2020). "In summary, we provided evidence that MSI-N1014 suppressed the major colon cancer stemness markers, LGR5 and β-catenin, and oncogenic signaling, such as mTOR and IL-6; it also prevented cancer cell-mediated CAF transformation." (PMID 32560222, 2020). "MicroRNA-100 has been found to function as a tumor suppressor by inhibiting Lgr5 expression in colon cancer cells." (PMID 33379338, 2020). "This localization correlates with the cytoplasmic localization of LGR5 within a colon cancer stem cell." (PMID 32256979, 2020). "MSI-N1014 was shown to function in suppressing the colon cancer stemness markers, LGR5, and β-catenin, while also preventing the transformation of CAFs." (PMID 32560222, 2020). "Mll1 is highly expressed in Lgr5+ stem cells and human colon cancer specimens with high levels of nuclear β-catenin." (PMID 33349639, 2020). "There is a similar report in colon cancer where both mice model and patients with Lgr5 positive tumors had decreased survival rates." (PMID 31814939, 2019).
colon carcinoma (continued). "CSCs plasticity in colon cancer has been well documented; as a consequence, targeted ablation of Lgr5+ cells is not sufficient to eradicate tumours as other cells can revert to Lgr5+ CSCs and contribute to tumour re-growth upon an initial regression." (PMID 30696875, 2019). "A monoclonal antibody against Lgr5 in colon cancer showed the suppression of Lgr5, Wnt pathway in CSCs and tumor volume reduction." (PMID 30841635, 2019). "Recently, a lineage tracing study in intestinal and colonic tumours using two stem cell-specific promoters, Lgr5 and Bmi17, proposed that these two ISCs markers can be used to detect different stem cell populations in intestinal tumours." (PMID 30696875, 2019). "In 2002, van de Wetering and colleagues identified leucine-rich repeat-containing G-protein-coupled receptor 5 (LGR5) as a gene upregulated by aberrant Wnt signaling in human colon cancer cells." (PMID 30733598, 2019). "In lung cancer and colon cancer an elevated LGR5 expression was found to correlate with tumor-size, tumor-stage, metastasis and poor outcome." (PMID 30770730, 2019). "Lgr5-expressing cells have been found in many tumors, such as colon cancer 26, 27, papillary thyroid cancer 28, breast cancer 29, and gastric cancer." (PMID 31754399, 2019). "Simultaneously, a similar study further confirmed the tumor eradicative and recurrence-preventive effects through Lgr5-targeted antibody-drug conjugates in a xenograft model of colon cancer." (PMID 31358061, 2019). "A recent study reported that targeting Lgr5+ cells with an antibody conjugated to distinct drugs exhibited potent efficacy to decrease tumor size and proliferation of colon cancer." (PMID 31358061, 2019). "Numerous reports have demonstrated LGR5 overexpression in colon cancer, and this correlates with increased proliferation and chemoresistance." (PMID 31608135, 2019). "A trend towards higher expression of Lgr5 and Opn in colon tumors of AOM treated Apc1638N/+ mice was observed." (PMID 31681563, 2019). "LGR5 is a marker gene for detection of CSCs in colon cancer 19,20, indicating differentiation capacity and self-renewal for LGR5+ tumor cells." (PMID 31057717, 2019). "The generation of Lgr5+ cells from Lgr5− cells after Lgr5+ ablation was also observed in the xenograft mouse model of human colon cancer stem cells (CSCs)." (PMID 31905853, 2019). "LGR5 expression was explored in various types of colon tumors, particularly concerning the localization of LGR5+ cells within the tumoral tissue." (PMID 29652830, 2018). "Analysis of primary colon cancer tissues showed the existence of both epiregulin+ LGR5+ and epiregulin+ LGR5− colon cancer stem cells: both these cell populations displayed a tumor-initiating capacity." (PMID 29652830, 2018). "Correspondingly, the expression levels of stem cell-associated genes, including OCT4, Lin28, Lgr5, KLF, Bmi-1, CD44 and SOX2, increased sharply in colon cancer cells upon treatment with exosomes from BM-MSCs or exosomal miR-142-3p." (PMID 30220706, 2018). "Consistently, qPCR analysis revealed that the expression of genes associated with colon cancer stem cells, including CD44, CD133, LGR5, and AXIN2, was reduced in SREBP1 and SREBP2 knockdown DLD1 and Pt130 cells." (PMID 29449559, 2018). "The large majority of colon cancers express both LGR5 and ASCL2 and the expression of these markers was positively correlated." (PMID 29652830, 2018). "Enrichment of Lgr5 and Ascl2 expression in the colon tumors of infected miR-34a-/- mice was further confirmed by western blot." (PMID 30543324, 2018). "We performed FCM and found that the exosome treatment increased the expression levels of CD133+ and Lgr5+ colon cancer cells." (PMID 30220706, 2018). "If these characteristics belong to the same lineage, the initiation and progression of colon carcinoma should be supported by the transition of Lgr5+ stem cells to self-renewing cancer stem cells." (PMID 28176811, 2017).
colon carcinoma (continued). "Clonal analysis using ubiquitous multicolor lineage tracing revealed that colon tumors derived from Lgr5-positive cells were monoclonal in origin but eventually merged with neighboring tumors, producing polyclonal tumors at the later stage." (PMID 28176811, 2017). "We established tumor organoids derived from the Apcmin/+ mouse, a model of colon cancer, using a new 3D culture system that allows Lgr5-positive stem cells to form cyst-like structures (organoids)." (PMID 28545228, 2017). "33P-LGR5 in situ signals in adjacent benign hyperplastic colon crypts were restricted to their crypt base origin in contrast to their diffuse invasiveness in primary human LGR5+ colon carcinomas." (PMID 26744320, 2016). "GSEA of stage I colon carcinomas showed significant activation of the embryonic SC-like program in LGR5− compared to LGR5+ tumors." (PMID 26744320, 2016). "Initial stratification of stage I colon carcinomas based on either LGR5 or KRAS status showed activation of the EMT program in those with LGR5− or KRASwt status." (PMID 26744320, 2016). "We confirmed that relative to those with LGR5+ and KRASmut status, LGR5−/KRASwt colon carcinomas had decreased CDH1 and increased VIM and SLUG expressions, which are the expected changes in EMT biomarkers." (PMID 26744320, 2016). "Both Rnf43 and Znrf3 are ubiquitin ligases found specifically in Lgr5 crypt stem cells and enriched in colon cancer." (PMID 27187360, 2016). "One of recent report has shown that Lin28B promotes migration, invasion, and transformation by associating and repressing LGR5 and PROM1 mRNAs that are essential for colon cancer progression." (PMID 27821801, 2016). "We confirmed in a large and independent study cohort that LGR5 rs17109924 is a predictive genetic biomarker for TTR in patients with colon cancer treated with 5-FU-based adjuvant chemotherapy." (PMID 25665511, 2015). "In the intestine and colon, the Lgr5+ stem cells localized at the bottom of each colonic and intestinal crypt are believed to be the cells-of-origin from which intestinal and colon cancer develop." (PMID 26399194, 2015). "We were able to confirm that LGR5 rs17109924 is a predictive genetic biomarker for TTR in patients with colon cancer treated with 5-FU-based adjuvant chemotherapy." (PMID 25665511, 2015). "It would therefore be intriguing to assess the role of the GATA6/REG4 and GATA6/LGR5 pathways in the properties of colon cancer stem cells." (PMID 26387746, 2015). "We recently found variants in cancer stem cell genes (CD44, ALCAM and LGR5) significantly associated with increased time to recurrence (TTR) in patients with stage III and high-risk stage II colon cancer treated with 5-fluorouracil (5-FU)-based chemotherapy." (PMID 25665511, 2015). "In conclusion, we confirmed in a large and independent retrospective study cohort that LGR5 rs17109924 is a predictive biomarker for TTR in patients with colon cancer treated with 5-FU-based adjuvant chemotherapy." (PMID 25665511, 2015). "An understanding of the dynamics of intestinal Lgr5+ stem cells is important for elucidating the mechanism of colonic cancer development." (PMID 25832104, 2015). "The findings suggested that LGR5 plays a vital role in the maintenance of CCSCs and is a potential therapeutic target for colon cancer." (PMID 24789370, 2014). "More importantly, recent studies have demonstrated that almost all of the LGR5+ cells isolated from xenografts, generated by the sorted LGR5+ colon cancer cells, were positive for CD133 and CD166." (PMID 24789370, 2014). "Lgr5 is an established intestinal stem cell marker and has also been shown to regulate tumorigenic capacity of colon cancer cells." (PMID 24997475, 2014). "In this study, we identified an increased expression of LGR5 on the surface of spheroid cells by flow cytometry, indicating that these CSCs-enriched colon cancer cells contained a high proportion of LGR5+ cells." (PMID 24789370, 2014).
colon carcinoma (continued). "Recently, a signature that predicts disease relapse in colon cancer in man was developed based on mouse intestinal stem cells (ISC) expressing high levels of the Lgr5 and EphB2 genes." (PMID 24069241, 2013). "In another study, the orphan G protein-coupled receptor GPR49 (LGR5) was found to be overexpressed in primary human colon tumors and LGR5 was then found, in rodent studies, to be a SC marker." (PMID 24224156, 2013). "Another stem cell marker in the colon Lgr5 was also studied to further confirm the activity of BMW on colon cancer stem cells." (PMID 23533514, 2013). "In order to better recognize the SP cells directly by microscopy, we first used immunofluorescence to observe and analyze the colon cancer cells expressing Lgr5 after Hoechst33342 staining." (PMID 23153436, 2012). "For LGR5, earlier studies suggest that it has increased expression in colon cancer and basal cell carcinoma with expression potentially enriched in cancer stem cells." (PMID 22615920, 2012). "To achieve this, we selected SP cancer stem cells by Hoechst 33342 extrusion and used immunocytochemistry to explore the expression of Lgr5 in Hoechst33342 low-staining cancer cells in the colon cancer cell line, Colo205." (PMID 23153436, 2012). "The differential expression of Lgr5 between Hoechst 33342 low-staining cells and high-staining cells in colon cancer was observed and analyzed microscopically, and provided useful information for the clinical diagnosis and treatment of CSCs." (PMID 23153436, 2012). "LGR5 was reportedly expressed in murine stem cells of the intestinal crypts and was frequently overexpressed in colon cancer cell lines." (PMID 22530031, 2012). "In the in vitro study, Hoechst low-staining cells were counted in 7% of the Colo205 colon cancer cell line population, and Lgr5 expression was strikingly stronger in Hoechst low-staining cells than in high-staining cells (P=0.001)." (PMID 23153436, 2012). "LGR5, for example, showed oncogenic properties in colon cancer cells and basal cell carcinoma cells, but displayed tumor suppressor function in colon cancer cell lines with β-catenin mutations." (PMID 22615920, 2012). "The immunofluorescent staining of CD133/Lgr5 (colon cancer stem cell marker) and blood vessel EC marker CD31 were performed." (PMID 22745705, 2012). "In colonic tumor organoids derived from cis-Apc+/−Cdx1+/− and Cdx2+/−-cis-Apc+/−Cdx1+/− mice, the expression of Cdx1 and Cdx2 was lower than that in Apc+/− tumor organoids, whereas that of Lgr5 was higher." (PMID 40399276, 2025). "We previously studied mRNA biomarkers that correlated with poor prognosis in colon cancer (CC) patients, such as leucine-rich repeat-containing G protein-coupled receptors 5 and 6 (LGR5 and LGR6), as well as C-X-C motif chemokine ligands 16 and 17 (CXCL16 and CXCL17)." (PMID 40909962, 2025). "Targeting Lgr5+ cells to treat colon cancer has been a topic of interest, as these cells have demonstrated the potential to be the origin of some intestinal tumors; thus, we aim to thoroughly discuss the latest therapeutic strategies that target Lgr5+ cells." (PMID 39183418, 2024). "Anti-LGR5 ADCs have been shown to be effective in preclinical models of colon cancer." (PMID 39065640, 2024). "Moreover, another study revealed that colon cancer tissue is structured similarly to the normal colon epithelium with LGR5+ stem cells that give rise to KRT20+/LGR5− differentiated cells." (PMID 39358322, 2024). "Thus, LGR5 represents the‘ideal’ CSC marker for colon cancer as it can be used for CSCenrichment and lineage tracing, and targeting." (PMID 39822777, 2024). "This regulation was also found in representative upregulated genes for CMS2, including the WNT pathway target gene LGR5, which is an important marker of colon cancer stem cells, and the oncogenic transcription factor MYC, which regulates tumour growth, differentiation, and proliferation." (PMID 38339195, 2024).